MIR5701-1 (microRNA 5701-1)
Synonyms: hsa-mir-5701-1
Gene: MicroRNA gene on chromosome 15 (20,940,252 to 20,940,333, forward strand). Ensembl gene ENSG00000266545.
Homologues: Paralogues in human: MIR5701-2 (100% identical), MIR5701-3 (100% identical).